TET1 (tet methylcytosine dioxygenase 1)
Diseases named in the same sentence as TET1 in open-access papers (continued):
Sharing a sentence is not in itself a finding about the gene and the disease.
metastatic disease (1 paper, 2019). "In addition to CTNNB1‐activating mutations, we found inactivating mutations of epigenetic regulators (KDM6A, TET1, BAP1) associated with metastatic disease." (PMID 30306561, 2019).
neuropathy (1 paper, 2025). A disorder affecting the nervous system that manifests with pain, tingling, numbness, and/or muscle weakness. "In OXA-induced neuropathy, decreased TET1 reduces miR-30b, elevating Nav1.6 expression and currents and contributing to pain." (PMID 39864621, 2025). "We established a chemotherapy-induced neuropathy model using intraperitoneal oxaliplatin (OXA) injections and measured TET1 and Nav1.6 protein in the DRG." (PMID 39864621, 2025).
oligodendroglioma (1 paper, 2019). A well-differentiated (WHO grade II), diffusely infiltrating neuroglial tumor, typically located in the cerebral hemispheres. "Variants in tumor associated genes not typically associated with oligodendroglioma were also found, such as missense variants in TET1 (NM_030625:c.4399G>A; p.Glu1467Lys) and TGFBR2 (NM_003242:c.426G>C; p.Glu142Asp as well as a frameshift variant in ARID1A (NM_006015:c." (PMID 31217899, 2019).
oral squamous cell carcinoma (1 paper, 2024). "Silencing TET1 increases cisplatin sensitivity by altering the expression of multiple genes in various pathological conditions including vimentin in OVCA, and o6-methylguanine-DNA methyltransferase (MGMT) in oral squamous cell carcinoma (OSCC)." (PMID 38216951, 2024).
post-traumatic stress disorder (1 paper, 2016). An anxiety disorder precipitated by an experience of intense fear or horror while exposed to a traumatic (especially life-threatening) event. "Mice deficient in TET1 alone have deficits in memory extinction, a behavioral mechanism allowing adaptation that might be impaired in cases of post-traumatic stress disorder." (PMID 26989192, 2016).
primary hypogonadism (1 paper, 2024). "The reduced expression of Tet1 resulted in hypermethylation of several testosterone synthesis genes, including Lhcgr and Gnas, impaired Leydig cell function and ultimately led to transgenerational primary hypogonadism." (PMID 38649348, 2024).
retroperitoneal neuroblastoma (1 paper, 2023). A neuroblastoma that involves the retroperitoneal space. "Importantly, all models in the retroperitoneal subgroup were significant, indicating a significant association between TET1 gene polymorphisms and increased risk to retroperitoneal neuroblastoma." (PMID 37347215, 2023).
scurvy (1 paper, 2022). A condition that develops in people who do not consume an adequate amount of vitamin C in their diet. "Importantly, deletion of 5hmC-writers, Tet1 and Tet2, in Vitamin C-sufficient murine bone causes severe skeletal defects which mimic bone phenotypes of Vitamin C-insufficient Gulo knockout mice, a model of Vitamin C deficiency and scurvy." (PMID 36202795, 2022).
serous carcinoma (1 paper, 2024). "Similarly, we observed that high TET1 expression was significantly (p = 0.00045) associated with shortened PFS (14 months) compared with patients with lower TET1 expression (18 months) in serous carcinoma patients." (PMID 38216951, 2024).
smooth muscle tumor (1 paper, 2015). A benign or malignant myomatous neoplasm arising from smooth muscle. "Given that that oxidation of 5mC to 5hmC is considered to be a nuclear event, these results suggests TET1 is not the main player in the hydroxylation of 5mC in FH-deficient smooth muscle tumors." (PMID 26472283, 2015). "In contrast, FH-deficient smooth muscle tumors showed nuclear exclusion of TET1 in only 40% of cases and exclusion was not correlated with loss of 5hmC." (PMID 26472283, 2015). "Using immunohistochemistry, we investigated the distribution of 5mC, 5hmC, TET1, and histone methylation in SDH- mutant PGL/PCC and in FH-deficient smooth muscle tumors in comparison to non-SDH or FH-mutated PGL/PCC and smooth muscle tumors, respectively." (PMID 26472283, 2015).
teratocarcinoma (1 paper, 2019). A germ cell tumor characterized by the presence of an embryonal carcinoma component and a teratoma component. "Another study has shown using a murine teratocarcinoma cell line, ATDC5, that TET1 promotes chondrogenesis and 5hmC by short hair pin RNA." (PMID 30606231, 2019).
testicular germ cell tumor (1 paper, 2024). A germ cell tumor arising from the testis. "Further investigation into the tumor stem cell index revealed a positive correlation between heightened TET1 expression and increased levels of ribonucleic acid synthesis (RNAss) and deoxyribonucleic acid synthesis (DNAss) in testicular germ cell tumors (TGCT)." (PMID 39104395, 2024).
tumor (243 papers, 2012 to 2025). "TET1 exhibited a notably high mutation frequency across various tumor types, with missense mutations being the most prevalent." (PMID 40394037, 2025). "TET1 maintains hydroxymethylation at the promoters of these genes, and its loss has been associated with increased tumor growth, migration, and invasion." (PMID 40520993, 2025). "Specifically, TET1 deficiency has been linked to increased tumor cell invasion and enhanced xenograft tumor growth in breast and prostate cancer models, highlighting its potential as a therapeutic target." (PMID 40663150, 2025). "One notable example is TET1, which encodes an enzyme involved in DNA demethylation and is generally regarded as a tumor suppressor." (PMID 40430005, 2025). "Wielscher et al31 found decreased mRNA expression of both leucine zipper tumor suppressor 1 (LZTS1) and TET1 in tumor samples, with reductions in 5hmC levels linked to unfavorable histopathological features, including lymph node involvement." (PMID 40520993, 2025). "While TET1 demonstrates only limited correlation with tumor staging, TET2 exhibits significant associations in STAD, LIHC, and LUAD (p < 0.01)." (PMID 39104395, 2024). "Loss of TET1 has been associated with hypermethylation of tumor suppressor genes, thereby leading to their inactivation." (PMID 37020036, 2023). "Here, we find that high TET1 expression is associated with poor patient survival in solid cancers often having hypoxia, which is inconsistent with its tumor suppressor role." (PMID 37020036, 2023). "Compared with the wild-type patients, TET1-mutated patients had higher tumor mutational burden and neoantigen load, enhanced abundance of tumor-infiltrating immune cells, increased expression of immune-related genes, and mutation number of DDR pathways." (PMID 35395805, 2022). "Second, the effects of TET1 mutations on the CNVs, tumor immunogenicity, antitumor immunity, GSEA, and drug sensitivity were not analyzed in the ICI-treated cohort due to use of a single-targeted NGS panel and the absence of gene expression data." (PMID 35395805, 2022). "Rescue experiments in vivo were performed to further confirm the critical the Wnt/β-catenin pathway played in tumor suppressor caused by TET1 deregulation." (PMID 34926132, 2021). "TET1, as DNA demethylase, is thought to be associated with tumor metastasis, and hypoxia increases the expression of TET1 in a HIF-1α-dependent manner." (PMID 33109235, 2020). "We found that TET1 protein level is significantly associated with T stage (p = 0.002) and tumor grade (p < 0.001)." (PMID 32528872, 2020). "Xenograft tumor experiment was conducted to confirm the association between TET1 and P‐gp expression under gemcitabine chemoresistance." (PMID 30784212, 2019). "The study also found that macrophage-derived cytokine IL17A stimulates the expression of ERα in tumor cells through relieving the methylation-linked inactivation of ERα via upregulating the expression of TET1." (PMID 31426393, 2019). "In TCGA dataset, TET1-MUT was strongly associated with higher tumor mutational burden and neoantigen load, and inflamed pattern of tumor-infiltrating T lymphocytes, immune signatures and immune-related gene expressions." (PMID 31623662, 2019). "In the tumor of patient ID90 we identified a missense variant in the candidate gene TET1 (p.(Val128Leu)) with an allele frequency of 26.1%." (PMID 31212687, 2019). "TET1-MUT was found to be significantly associated with enhanced tumor immunogenicity and inflamed anti-tumor immunity." (PMID 31623662, 2019). "Accordantly, the neoantigen load was also significantly higher in TET1-MUT tumors (P < 0.001), indicating that TET1-MUT was associated with enhanced tumor immunogenicity." (PMID 31623662, 2019). "Loss of TET1 expression through promoter CpG methylation frequently occurs in tumor cells, which results in tumor pathogenesis via inactivation of tumor suppressor genes." (PMID 31796082, 2019).
tumor (continued). "TET1 deficiency not only causes cell genomic instability, a hallmark of cancer, but also leads to tumorigenesis and tumor vascular invasion." (PMID 30551127, 2018). "In tumours with loss of 5-hmC, expression of TET1 was more prominent in the cytoplasm than the nucleus (p = 0.0001)." (PMID 28484589, 2017). "We subsequently performed a (h)MeDIP-Seq analysis of the DNA from the patient whose tumor carried the TET1 mutation, and compared it with that of the seven other patients with wild type TET1 genes." (PMID 27014907, 2016). "A significantly higher tumor weight was associated to PAs displaying a more severe aberrant staining pattern of 5hmC and TET1." (PMID 26973719, 2016). "A significantly higher tumor weight was found associated to PAs that displayed a more severe aberrant staining pattern of 5hmC and TET1." (PMID 26973719, 2016). "When comparing (h)MeDIP-Seq data of tumor DNA from seven samples with wild type TET1 versus one sample with the A1908S mutation using diffReps, we detected 33 differentially methylated regions and 933 differentially hydroxymethylated regions." (PMID 27014907, 2016). "Additionally, loss of TET1 enhances tumor adaptive metabolism by upregulating hypoxia-inducible factor 1-alpha (HIF-1α) signaling." (PMID 41394878, 2025). "For example, TET1 mutation has been strongly associated with increased tumor immunogenicity and could be used as a potential biomarker for immune checkpoint blocker therapy in multiple cancers." (PMID 38317133, 2024). "Additionally, the tumor immunogenicity and antitumor immunity were also analyzed between TET1-mutated and wild-type patients." (PMID 35395805, 2022). "However, TET1 acts as a tumor suppressor gene and TET1 inhibition is linked to cancer suggesting systemic delivery would be undesirable." (PMID 34774787, 2022). "Moreover, in the context of TET1 mutations, the tumor immunogenicity and antitumor immunity were reinforced." (PMID 35395805, 2022). "The effect of 5hmC has also been associated with tumour suppressor mechanisms: downregulation of TET1 and 5hmC were associated with transcription of SFRP2, which prevents tumour progression trough impairment of WNT pathway, that promotes EMT and cancer progression." (PMID 34944974, 2021). "Notably, the underexpression of TET1 in GC tissues was markedly associated with larger tumor size, lymphatic metastasis and poor differentiation of cancer tissues." (PMID 33088215, 2020). "To determine whether loss of TET1 function affects tumor cell proliferation and viability, we carried out shRNA-mediated TET1 knockdown (KD) in human T-ALL cells (CCRF-CEM)." (PMID 31266538, 2019). "Besides, although TET1-MUT was found to be strongly correlated with enhanced tumor immunogenicity and inflamed anti-tumor immunity, the underlying molecular mechanism of TET1-MUT sensitizing patients to ICI treatment still requires further exploration." (PMID 31623662, 2019). "Moreover, transcriptional inactivation of SALL3 was associated with aberrant methylation of other tumor-related genes and TET1, TET2, and DNMT3A levels in HNSCC." (PMID 28616099, 2017). "To test for functional significance of TET activity during differentiation, we performed TET1 knockdown experiments since TET1 was induced during differentiation and since TET1 has been implicated as a tumor suppressor and regulator of the WNT pathway in carcinomas, including colon cancer." (PMID 26631571, 2015). "In addition, in xenograft models, TET1 deficiency facilitated tumor growth and metastasis." (PMID 37430206, 2023). "Thus, a more severe aberrant staining pattern of 5hmC and TET1 associated to tumor mass and may therefore interfere with the tumor cell growth regulatory control." (PMID 26973719, 2016). "To investigate potential drivers of DNA hypermethylation in ALL, we analyzed TET1, a crucial demethylating enzyme with tumor suppressive functions." (PMID 41254398, 2025).
tumor (continued). "Yet, emerging research presents a more complex narrative, revealing that TET1 displays variable expression across different tumor types and subtypes, triggering distinct biological effects by regulating diverse genes in various signaling pathways." (PMID 40520993, 2025). "Inhibition of EGFR allowed TET1 to bind to tumor suppressor promoters, reactivating their expression via DNA demethylation and significantly inhibiting tumor growth." (PMID 40520993, 2025). "TET1 promotes tumor growth by regulating genes involved in ribosomal biogenesis, while TET2 suppresses tumorigenesis." (PMID 40520993, 2025). "Given the tumor-like migratory behavior of trophoblast cells, wound-healing assay were used to assess the impact of TET1 overexpression." (PMID 41165593, 2025). "Combining TET1 inhibition with chemotherapy enhanced this effect, highlighting its dual role in both tumor progression and therapeutic response." (PMID 40520993, 2025). "Knockdown of GATA6 or TET1 attenuated CAF-mediated tumor growth in vivo, underscoring their potential as therapeutic targets." (PMID 40216762, 2025). "Using a CRISPR-based epigenetic editing tool reactivated CLDN10B to its endogenous level using VP160 and TET1 by promoter demethylation and significantly demonstrated its tumor-suppressive effects in 2D and 3D cell models." (PMID 40524239, 2025). "We found that tumor size in mice injected with GATA6- or TET1-depleted CAFs were ~20% smaller than those in the control group (Mice transplanted with scramble siRNA-transfected CAFs) (P < 0.05)." (PMID 40216762, 2025). "For example, TET1 expression and 5hmC levels are decreased in tumor samples from luminal A, luminal B, and HER2-positive subtypes compared to normal breast tissue samples." (PMID 39966373, 2025). "By removing methyl groups from specific tumor suppressor genes, TET1 can influence their expression." (PMID 40520993, 2025). "Moreover, TET1 expression was elevated in some tumors and may be linked to tumor aggressiveness." (PMID 40394037, 2025). "Previous studies have shown that Dox-induced TET1 overexpression suppresses cancer cell proliferation and tumor growth." (PMID 41165593, 2025). "Immunohistochemical staining revealed a significant reduction in Ki67-positive cells in tumors derived from GATA6- or TET1-depleted CAFs (P < 0.01 vs. control), indicating suppressed tumor cell proliferation." (PMID 40216762, 2025). "Dysregulation of TET1 function or alterations in its genetic structure can disrupt epigenetic regulation, potentially contributing to tumor growth, metastasis, and other cancer-related processes." (PMID 40520993, 2025). "TET1 has been reported to have dual tumor-promoting and tumor-suppressing functions in cancer development, progression and treatment responses." (PMID 38216951, 2024). "The results showed that for tumor microenvironment-related scores, TET1 was significantly positively correlated with the three scores of PAAD, and negatively in LUAC." (PMID 39104395, 2024). "It has been reported that there are mainly two transcripts (TET1-FL and TET1-short) of TET1 in a variety of tumor cells." (PMID 38967794, 2024). "Conversely, in TNBC, TET1 expression is increased in tumor tissue samples compared to normal breast tissue samples, and its high expression correlates with poor patient outcomes." (PMID 38645113, 2024). "A positive relationship between tumor YAP1 and TET1 levels was then validated in MST1/2−/− mouse tumor tissues and clinical HCC tissues." (PMID 38967794, 2024). "TET1 is a tumor suppressor that is required for DNA demethylation, which counters the effects of DNA methyltransferase-induced CGI hypermethylation and gene expression suppression." (PMID 39500892, 2024). "TET1 exerts tumor suppressor function by hypomethylating tumor suppressor genes and reactivating their expression." (PMID 38216951, 2024).